SIRPA (signal regulatory protein alpha)
Diseases named in the same sentence as SIRPA in open-access papers (continued):
Sharing a sentence is not in itself a finding about the gene and the disease.
cancer (continued). "CD47 is an anti-phagocytic “don't eat me” signal expressed by almost all cancer cells to evade the immune system by binding to the signal regulatory protein alpha (SIRPα) located on phagocytes, including macrophages." (PMID 34765437, 2021). "Various cancer types including solid tumors as well as hematological malignancies have shown to harness the SIRPα/CD47 pathway to evade immune surveillance by overexpressing CD47." (PMID 34276685, 2021). "To date, most efforts focused on targeting CD47 by using blocking antibodies, especially in the purpose of disrupting CD47/SIRPα signaling to promote cancer-cell phagocytosis." (PMID 34638503, 2021). "Combining the CD47 blocking domain, such as endogenous SIRPα, with a cancer-specific antibody in a single molecule can restrict the blockade of CD47 locally on antigen-expressing cells." (PMID 34579739, 2021). "First, the interaction between CD47 on cancer cells and SIRPα on the surface of macrophages leads to diminished cytoskeleton activity, which is reflected by decreased non-muscle myosin and actin in the phagocytic synapse." (PMID 34944878, 2021). "The role of the CD47/SIRPα interaction in providing an escape mechanism for cancer cells from macrophage targeting has been well described." (PMID 34944850, 2021). "CD47 interacts with the signal-regulatory protein alpha (SIRPα) on the surface of phagocytic cells, weakening the ability of macrophages to engulf cancer cells." (PMID 34503245, 2021). "Under hypoxic conditions, HIF-1 induces CD47, overexpressed in many cancers who can bind with SIRPα (signal regulatory protein alpha), an inhibitory receptor which is mostly located on macrophages." (PMID 34595122, 2021). "therefore performed a SIRPα knockout (KO) in the murine monocyte/macrophage cell line RAW264.7 using CRISPR-Cas9 and demonstrated that SIRPα-KO macrophages in this system exhibited enhanced phagocytic ability against cancer cells in vitro." (PMID 34899748, 2021). "Elevated CD47 expression on some cancer cells protects tumors from innate immune surveillance and limits adaptive antitumor immunity via inhibitory SIRPα signaling in antigen-presenting cells." (PMID 34717705, 2021). "Our study provides proof-of-principle for developing Sirpα−/− macrophage-based therapies to cure a broad spectrum of cancers including those at advanced stages with metastasis." (PMID 34050181, 2021). "CD47 on cancer cells interacts with signal regulatory protein alpha (SIRPa) on macrophages/microglia to signal a block in their phagocytosis." (PMID 33214223, 2021). "The binding of CD47 expressed on cancer cells to SIRPα expressed on macrophages inhibits phagosome formation preventing the engulfment of cancer cells." (PMID 33919517, 2021). "CD47 functions by binding to its cognate receptor called Signal Regulatory Protein Alpha (SIRPα) on macrophages and dendritic cells, leading to disruption of the phagocytic synapse site, and ultimately preventing phagocytosis of the cancer cell." (PMID 34829860, 2021). "The interaction between cluster of differentiation 47 (CD47) on cancer cells and signal regulatory protein alpha (SIRPα) on immune cells, such as macrophages and dendritic cells, generates a “don’t eat me” signal." (PMID 34944850, 2021). "Currently, 10 CD47 antibodies and four SIRPα fusion proteins are being evaluated for clinical efficacy in various type of cancer." (PMID 33449453, 2021). "CD47 protects healthy cells from macrophage attack by binding to signal regulatory protein α (SIRPα), while its upregulation in cancer prevents immune clearance." (PMID 34729396, 2021). "An interesting example is RRx-001, which downregulates CD47 on cancer cells and SIRPα on monocytes and stimulates TAMs against cancer cells." (PMID 33919517, 2021). "Dendritic cells (DC) express increased SIRPα in cancer, inducing immune tolerance, decreasing DC survival and activation, and suppressing the cytotoxic T cell response." (PMID 35582455, 2020).
cancer (continued). "CD47, a “don’t eat me” signal activated via an interaction with signal regulatory protein α (SIRPα) on innate immune cells such as macrophages and DCs, is regarded as an innate immune checkpoint in cancer." (PMID 33168028, 2020). "Signal regulatory protein alpha (SIRPα) and CD47 have an important role during cancer progression and blocking CD47-SIRPα interaction has been shown to promote the destruction of cancer cells by phagocytes, macrophages, and neutrophils." (PMID 32210958, 2020). "One of these receptors, CD47, also known as the “don’t eat me” signal, has been found to be overexpressed by most cancer histologies and has been successfully targeted by antibodies blocking the receptor or its ligand, signal regulatory protein α (SIRPα)." (PMID 35582455, 2020). "A growing body of evidence demonstrates that CD47 is overexpressed in various hematological malignancies and its interaction with SIRPα on the phagocytic cells prevents phagocytosis of cancer cells." (PMID 32677994, 2020). "We demonstrated that the oncolytic adenovirus SG635‐SF armed with the SIRPα‐Fc fusion gene exhibited a great inhibitory effect on CD47‐positive cancer cells both in vitro and in vivo." (PMID 31899582, 2020). "Firstly, by cell to cell contact through CD47 (cancer cell) and SIRPα (macrophage) binding, CCR2, or CX3CR1 chemokine receptors; Secondly, through soluble factors or exosomes loaded in IL-10." (PMID 32477352, 2020). "The disruption of CD47/SIRPa-signaling increases macrophage mediated phagocytosis of diseased vascular tissue and cancer cells." (PMID 32882841, 2020). "It is known that cancer cells express the CD47 receptor to manipulate macrophages that escape immune surveillance; blockage of the CD47/signal regulatory protein alpha (SIRPα) axis increases phagocytosis of cancer cells and immune responses." (PMID 32486019, 2020). "Cancer cells can also hijack innate immune checkpoints including the CD47–signal regulatory protein alpha (SIRPα) phagocytosis checkpoint." (PMID 32645996, 2020). "CD47 forms a signaling complex with signal-regulatory protein α (SIRPα), enabling the escape of these cancer cells from macrophage-mediated phagocytosis." (PMID 32082311, 2020). "The mRNA and protein levels of macrophage ELK-1 and SIRPα in carcinoma tissue samples were much higher than those in adjacent normal tissue samples." (PMID 32296015, 2020). "With the advent of cancer immunotherapy, SIRPα/CD47 immunotherapy with an aim to activate the innate immune system has drawn tremendous interest in treating cancer patients." (PMID 31611550, 2019). "Another potentially successful strategy for cancer therapy is the combination of a molecule that blocks SIRPα with Abs specific for tumoral antigens." (PMID 31921125, 2019). "CD47 is a “don't eat me” signal, which prevents cancer cells from phagocytosis by binding to signal regulatory protein alpha on macrophages." (PMID 30938231, 2019). "Disrupting the interaction between CD47 and SIRPα on cancer cell surface by blockade or down-regulation of CD47 efficiently promoted phagocytosis by macrophages in vitro and in vivo." (PMID 31139022, 2019). "CD47 molecule, a ubiquitous cell-surface receptor that promotes immune evasion by interacting with signal-regulatory protein alpha (SIRPα), is a member of immunoglobulin (Ig) superfamily and is considered as a promising cancer biomarker." (PMID 31461846, 2019). "We next investigated the therapeutic impact of mAbs blocking CD47 and/or SIRPα on gastroenterological tumors in immunocompetent mouse models equipped with syngeneic immune responses between cancer and immune cells." (PMID 30460349, 2018). "We have previously found that antibodies that block the interaction of CD47 with macrophage surface SIRPα release the macrophage to phagocytose and destroy the cancer cells." (PMID 28378740, 2017).
cancer (continued). "Expression of CD47 and its interaction with SIRPa leads to the inhibition of macrophage activation and protects cancer cells from phagocytosis, resulting in cancer cell proliferation." (PMID 29312320, 2017). "We observed an exclusively abundant expression of MUC16 and SIRPA in the dysplastic lesions and the corresponding carcinoma tissues of this patient." (PMID 28383029, 2017). "Failure to induce SIRPα in cancer cells such as Huh7 cells yielded the poor effect of ATO treatment on their apoptosis." (PMID 27010069, 2016). "Studies have demonstrated that macrophage phagocytosis is the major mechanism when treating cancer using antibody therapies aimed to abolish the interaction between CD47/SIRPα." (PMID 27671753, 2016). "Flow cytometric analysis was applied to study the effect of cancer cells on the expression of SIRPα on macrophages." (PMID 27793032, 2016). "Signal regulatory protein α (SIRPα) has been shown to operate as a negative regulator in cancer cell survival." (PMID 27010069, 2016). "Interestingly, strategies with SIRPα-blockade with antibodies to induce phagocytosis of cancer cells are also now being tested." (PMID 41484790, 2026). "Collectively, these therapeutic strategies, including oncolytic vectors, neutralizing antibodies, Fc-engineered fusion proteins, and small-molecule inhibitors, highlight the centrality of SIRPα-mediated immune suppression in cancer and offer versatile avenues for therapeutic intervention." (PMID 41486149, 2026). "On one hand, CD47 overexpression allows cancer cells to evade immune clearance by binding to SIRPα." (PMID 40016734, 2025). "Cancer cells upregulate CD47 expression to promote immune escape through activating the “don’t eat me” signal via interactions with signal regulatory protein α (SIRPα) on macrophages." (PMID 40578556, 2025). "We also present the research progress made toward anti-SIRPα antibody cancer therapies and discuss why a SIRPα-targeting strategy may be a valuable choice." (PMID 40589735, 2025). "The immunosuppressive receptor known as signal regulatory protein α (SIRPα), expressed on myeloid cells, was developed and has received a lot of attention because of its function in mediating the immunosuppressive “don’t eat me” signal from cancer cells." (PMID 40589735, 2025). "CD47–SIRPα signaling is involved in the development of diseases including cancer, and since short SIRPα is expressed as widely as long SIRPα, we believe that these findings will provide important perspectives into the mechanisms of onset and the development of treatments for these diseases." (PMID 40763927, 2025). "One of the top ligands induced by Mφs (i.e., expressed higher in CAFs in the Tri condition than CoCAF) was signal regulatory protein alpha (SIRPA), which is a well‐known ligand that mediates cancer immune evasion by activating the CD47 expression on cancer cells." (PMID 40056038, 2025). "In brief, targeting SIRPα may constitute a prospective path for future research in cancer immunotherapy, and studying the role of endogenous SIRPα in cancer cells and progression has significant scientific value." (PMID 40589735, 2025). "Indeed, anti-CD47 antibodies or SIRPα-Fc fusion proteins inhibit the “don’t eat me” signal by blocking the CD47- SIRPα axis and unmask the “eat me” (pro-phagocytic) signals expressed on cancer cells, thus promoting macrophage phagocytosis." (PMID 40369208, 2025). "We postulated that the SIRPα-αMSLN LicMAb specifically blocks CD47 on MSLNpos cancer cells." (PMID 40402266, 2025). "The relevant mechanism may involve VISTA downregulating the anti-phagocytic signal SIRPα, which enhances the phagocytic capacity of M2 macrophages against cancer cells." (PMID 39286218, 2024). "Targeting CD47/SIRPα axis has emerged as a promising strategy in cancer immunotherapy." (PMID 38429732, 2024).
cancer (continued). "However, discerning SIRPα's intricate role in cancer immunity presents a challenge, and its precise regulatory function in anticancer immunity requires further elucidation." (PMID 38342925, 2024). "In summary, our research underscores the dual-targeting proficiency of the small-molecule compound SMC18 against both the CD47/SIRPα and PD-1/PD-L1 pathways, bridging innate and adaptive immunity and thus providing a promising candidate for cancer immunotherapy." (PMID 38462636, 2024). "Finally, we aimed to investigate the role of SPP1 + SIRPα + macrophages in cancer patient survival and the efficacy of immunotherapy." (PMID 39696410, 2024). "This may indicate that SIRPα-Fc treatment increases cancer cell survival, and CK2 may be a key player for EMT driven proliferation or spheroid formation." (PMID 38495618, 2024). "To date, many efforts have been made to block CD47/Sirpα to promote cancer cell phagocytosis." (PMID 38832992, 2024). "Our findings suggested that the small molecule compound SMC18, which dual-targets the CD47/SIRPα and PD-1/PD-L1 pathways, could be a candidate for promoting macrophage- and T-cell-mediated phagocytosis and immune responses in cancer immunotherapy." (PMID 38462636, 2024). "However, the molecular mediators and mechanisms regulating the expression of CD47 by cancer cells and SIRPα by macrophages remain poorly defined." (PMID 38183060, 2024). "The formation of complexes with CD47 and SIRPα transmits an antiphagocytic signal to macrophages, and the CD47-SIRPα pathway serves as an innate immune checkpoint to function as a druggable target, which enables cancer cells to escape from phagocytosis mediated by macrophages." (PMID 38177102, 2024). "Targeting CD47 to disrupt its interaction with SIRPα can enhance the immune system’s ability to destroy cancer cells and could be explored to prevent autoinflammatory diseases." (PMID 39039207, 2024). "Our findings showed that SPP1 + SIRPα + macrophages could be immune inhibiting and represented an unfavorable prognostic biomarker in cancer patients including ESCC and HCC." (PMID 39696410, 2024). "Despite the successful application of anti-CD47 and anti-SIRPα blocking antibodies in immunotherapy against cancer cells, the potential of engaging SIRPα to restrain excessive immune activation in the context of ILC2s and allergic lung inflammation remains unexplored." (PMID 39160226, 2024). "These fusion proteins, created by combining the CD47-binding domain of human SIRPα with either the human IgG1 or IgG4 Fc region, aim to enhance phagocytosis and anti-cancer activity of macrophages by blocking CD47-SIRPα contact between malignant cells and macrophages through Fc receptor engagement." (PMID 39040441, 2024). "Moreover, the overexpressed SIRPα on gCMs enhanced the cancer immunotherapy by disrupting the CD47-SIRPα signaling pathway." (PMID 38699238, 2024). "Furthermore, CD47 expressed on cancer cells and stromal cells can also interact with SIRPα on MDSCs and inhibit their activation and differentiation into mature macrophages and DCs." (PMID 38188674, 2023). "One such checkpoint, CD47, is a transmembrane protein overexpressed on the membrane of cancer cells that binds to signal-regulatory protein alpha (SIRPα) of innate immune cells, sending a “don’t eat me” signal and helping the escape of cancer cells from the immune system." (PMID 37759771, 2023). "Indeed, the blocking antibody against SIRPα on macrophages favors the phagocytosis of CD47-expressing cancer cells." (PMID 36829496, 2023). "CD47 protein, expressed in both healthy and cancer cells, plays a crucial role in blocking the cytotoxic activity of myeloid cells by delivering a “do not eat me signal” upon binding to the signal-regulatory protein alpha (SIRPα) receptor on macrophage cells." (PMID 37368179, 2023).
cancer (continued). "The interaction between CD47 on cancer cells and signal regulatory protein alpha (SIRPα) on myeloid cells transmits a signal that prevents the cancer cells from immune detection and phagocytosis, allowing them to evade immune clearance and proliferate unchecked." (PMID 38188674, 2023). "Blockade of SIRPα/CD47 interaction is effective in combinational therapy of some cancers." (PMID 36419386, 2023). "However, cancer cells often overexpress CD47, a “don’t eat me” signal that helps cancer cells evade TAM-mediated phagocytosis by interacting with its receptor SIRPα on TAMs." (PMID 36594466, 2023). "To this end, we applied MφNPs and SIRPα-blocked MφNPs to CFSE-stained cancer cells." (PMID 38111068, 2023). "Then, three-armed cancer-targeting OAds were developed: OAd-SIRPα-Fc and OAd-Siglec10-Fc, which expressed SIRPα-Fc or Siglec10-Fc, respectively, to target macrophages to restore the phagocytic capabilities of these cells, and OAd-TIGIT-Fc, which secreted TIGIT-Fc to reactivate T cells." (PMID 38016957, 2023). "CD47 is a transmembrane protein of the immunoglobulin (Ig) superfamily and is overexpressed in several cancers, which could directly bind with SIRPα to deliver the “don’t eat me” signal that exerts anti-phagocytosis function." (PMID 37334368, 2023). "In light of these obstacles, CD47/SIRPα-targeted BsAbs may be another promising strategy to fight cancer." (PMID 35978372, 2022). "Defective macrophage function may result from reduced CD206 and signal regulatory protein alpha (SIRPa) expression, as well as increased inducible nitric oxide synthase (iNOS), which aids cancer progression through NO production." (PMID 35735633, 2022). "The interaction of CD47 on cancer cells with SIRPα on macrophages could suppress the phagocytosis of macrophages." (PMID 36300110, 2022). "As the CD47/SIRPα cancer cell/Mφ axis is commonly expressed in NSCLC a therapeutic blockage could prove useful as adjuvant or neo-adjuvant immunotherapy in operable NSCLC." (PMID 35406573, 2022). "It is upregulated on cancer cells and interacts with SIRPα on the surface of TAMs." (PMID 35883493, 2022). "As TAMs expressing SIRPα are abundant in cancer, sSIRPα may function as a biomarker, and we envision two potential uses of sSIRPα." (PMID 35883493, 2022). "Finally, we demonstrate that SIRPa knocked-out MDMs can enhance activity against a CD47-expressing cancer cell line." (PMID 36077152, 2022). "Cancer cells escape macrophage phagocytosis by exploiting the CD47/SIRPα axis." (PMID 35406573, 2022). "Finally, we demonstrate that SIRPa knock-out monocyte-derived macrophages have enhanced activity against cancer cells, highlighting the potential for application in cellular immunotherapies." (PMID 36077152, 2022). "The CD47 cell surface molecule serves as a myeloid checkpoint: blockade of the interactions between CD47 expressed by cancer cells and SIRPα on the surface of macrophages alleviates a ‘don’t-eat-me’ signal, facilitating the phagocytosis of cancer cells by macrophages." (PMID 36411318, 2022). "The CD47/SIRPα axis has emerged as one of the most promising cancer immunotherapy targets." (PMID 35256517, 2022). "CD47/SIRPα innate immune checkpoint inhibitors have emerged as a new promising class of cancer immunotherapy that might synergize with treatments that invigorate antitumor T-cell response." (PMID 35538512, 2022). "Similarly, CD47, which promotes immune evasion by engaging signal-regulatory protein alpha (SIRPα) and serves as an inhibitory receptor on macrophages, is emerging as a novel macrophage immune checkpoint for cancer immunotherapy." (PMID 35547750, 2022). "Moreover, our analyses revealed correlations between EMT and immune checkpoints in early-stage LUAD, such as CD200, TNFSF4 and SIRPA, which have also been demonstrated in other types of carcinomas." (PMID 35645555, 2022).